SPINK4 (serine peptidase inhibitor Kazal type 4)
Synonyms: PEC-60; MGC133107; HEL136; PEC60
Tractability: Antibody: UniProt places it where antibodies can reach, with medium confidence; UniProt predicts a signal peptide or a membrane-spanning region; its Gene Ontology location is reachable by antibodies, with medium confidence.
Gene: Protein-coding gene on chromosome 9 (33,218,365 to 33,248,567, forward strand). Ensembl gene ENSG00000122711.
Subcellular location: Secreted
Subcellular location (Human Protein Atlas): Golgi apparatus; Vesicles; Nucleoplasm; Predicted to be secreted
Gene Ontology:
Molecular function: protein binding; serine-type endopeptidase inhibitor activity
Biological process: response to xenobiotic stimulus
Cellular component: extracellular region
Genetic constraint (gnomAD): Loss-of-function variants: 10 observed, 12.29 expected, observed/expected ratio (o/e) 0.81, 90% interval 0.5 to 1.38. The upper end of that interval is the gene's LOEUF score, 1.38, which puts it in group 5 of 6, group 1 being the genes least tolerant of losing a copy. Missense variants: 91 observed, 109.34 expected, observed/expected ratio (o/e) 0.83, 90% interval 0.7 to 0.99. Synonymous variants: 37 observed, 41.22 expected, observed/expected ratio (o/e) 0.9, 90% interval 0.69 to 1.18.
Homologues: Orthologues: macaque SPINK4 (90% identical), chimpanzee SPINK4 (80% identical), rabbit SPINK4 (74% identical), dog SPINK4 (73% identical), pig SPINK4 (73% identical), guinea pig SPINK4 (67% identical), rat Spink4 (65% identical), mouse Spink4 (63% identical), zebrafish spink4 (40% identical).
Diseases named in the same sentence as SPINK4 in open-access papers:
SPINK4 is named in the same sentence as 34 diseases in open-access papers, as found by Europe PMC text mining. Sharing a sentence is not in itself a finding about the gene and the disease. The quoted sentences say what the papers report.
colorectal cancer (11 papers, 2019 to 2025). A primary or metastatic malignant neoplasm that affects the colon or rectum. "Interestingly, it has been suggested that the serum SPINK4 level is increased in colorectal cancer patients and has high diagnostic utility, whereas the expression of SPINK4 has been reported to be reduced in colorectal cancer tumor specimens and associated with poor survival." (PMID 34202399, 2021). "The expression levels of TPM2, RPS17, and TNNT1 were significantly elevated, while SPINK4 expression was reduced in the epithelial cells of colorectal cancer with liver metastasis." (PMID 41127012, 2025). "During the metastasis process, we observed significant increases in the expression of the TPM2, RPS17, and TNNT1 genes in colorectal cancer epithelial cells, while SPINK4 expression was notably reduced." (PMID 41127012, 2025). "The loss of SPINK4 expression was detected in colorectal cancer (CRC) and lower SPINK4 expression was linked with reduced disease-free survival in CRC patients." (PMID 38892042, 2024). "We recently identified an RNA-sequencing profile that associates with CAT in colorectal cancer (CRC) patients, with REG4, SPINK4, and SERPINA1 as the top-3 upregulated genes at mRNA level." (PMID 38066386, 2024). "Little is known about the role of serine peptidase inhibitor Kazal type 4 (SPINK4) in colorectal cancer (CRC) and ferroptosis." (PMID 37013514, 2023). "Then, IHC staining was used to assess the levels of the SPINK4 protein in 81 colorectal cancer tissues compared with adjacent normal tissues." (PMID 31888570, 2019). "SPINK4 is prominently expressed in normal colorectal, small intestine, and stomach tissues, as well as in gastrointestinal cell lines, but its expression significantly declines in colorectal cancer (CRC) tissues." (PMID 41127012, 2025). "SPINK4 is also intriguing as it is linked to the regulation of glycolysis in colorectal cancer but is not well characterized in pancreatic cancers." (PMID 39684873, 2024). "The role of serum serine peptidase inhibitor, Kazal type 4 (SPINK4), in colorectal cancer (CRC) is largely unknown." (PMID 30976466, 2019). "The clinical significance of SPINK4 in colorectal cancer (CRC) is largely unknown." (PMID 31888570, 2019). "The expression levels of TPM2, RPS17, and TNNT1 progressively increased during the progression and metastasis of colorectal cancer (CRC); in contrast, SPINK4 expression initially rose before sharply declining." (PMID 41127012, 2025). "During liver metastasis in colorectal cancer, the expression levels of TPM2, RPS17, and TNNT1 were significantly elevated, SPINK4 expression was reduced in the epithelial cells." (PMID 41127012, 2025). "Circulating SPINK4 is a valuable factor in the diagnosis of colorectal carcinoma with no predictive value in survival." (PMID 38997284, 2024).
colon cancer (7 papers, 2019 to 2024). "ELF-1, binding to the SPINK4 promoter, influenced its expression, and elevated ELF-1 levels were associated with poorer prognosis in colon cancer." (PMID 38747892, 2024). "According to the GTEx database, SPINK4 is specifically overexpressed in normal colon tissue; a previous study and TCGA database indicated that SPINK4 expression was reduced in colon cancer tissues compared with normal tissues." (PMID 37013514, 2023). "The expression of SPINK4 was a independent prognostic predictor, and the knockdown of SPINK4 enhanced the proliferation and migration of colon cancer cells." (PMID 38097680, 2023). "Given the biological effects of SPINK4 in colon cancer was still uncertain, we therefore conducted a series of experiments to explore the role SPINK4 played in colon cancer." (PMID 38097680, 2023). "The curves present survival data for the two groups of colon cancer patients based on gene expression level (high or low) of SPINK4, RETNLB, ASRGL1, CLCA1, and FCGBP (rows)." (PMID 31337362, 2019). "The serum SPINK4 level was remarkably elevated in colon cancer compared with rectal cancer and was enhanced in the M1 stage compared with the M0 stage (p < 0.05)." (PMID 30976466, 2019). "Consequently, we explored the character of SPINK4 in colon cancer microenvironment as well as in other cancer types." (PMID 38097680, 2023). "In addition, the serum SPINK4 level in patients with colon cancer was significantly elevated compared with patients with rectal cancer, indicating that metastatic status and location of tumor affect the serum SPINK4 level." (PMID 30976466, 2019). "To date, only one study has explored the role of SPINK4 in colon cancer cells." (PMID 30976466, 2019). "The dose-dependent effect of SPINK4 on phosphorylated EGFR (Y1608) was measured in the intestinal cell line NCM460 and colonic cancer cell line HT-29." (PMID 38997284, 2024). "Suppression of SPINK4 counteracted ELF-1 overexpression effects, suggesting a therapeutic avenue targeting ELF-1/SPINK4 expression for colon cancer treatment." (PMID 38747892, 2024). "A previous study found that expression of SPINK4 was decreased in colon cancer cells when SPDEF was inhibited and resulted in terminal differentiation and maturation of intestinal goblet cells, suggesting that SPINK4 was involved in the pathogenesis of colon cancer." (PMID 30976466, 2019).
celiac disease (5 papers, 2013 to 2023). An autoimmune genetic disorder with an unknown pattern of inheritance that primarily affects the digestive tract. "SPINK4 has recently been identified as a risk locus for UC and increased expression is seen in untreated celiac disease." (PMID 23382912, 2013). "A previous study reported that SPINK4 was overexpressed in the intestinal epithelial cells in active celiac disease compared to that in inactive celiac disease." (PMID 37013514, 2023). "In previous reports, SPINK4 was found to be significantly upregulated in intestinal epithelial cells in active celiac disease." (PMID 30976466, 2019).
rectal cancer (5 papers, 2019 to 2023). A primary or metastatic malignant neoplasm that affects the rectum. "High SPINK4 expression is associated with advanced clinicopathological features and a poor response to neoadjuvant concurrent chemoradiotherapy in patients with rectal cancer." (PMID 37007145, 2023). "In contrast, Chen and colleagues showed that high expression of SPINK4 is related to the advanced clinicopathological characteristics and poor treatment response of rectal cancer patients receiving chemotherapy." (PMID 38023180, 2023). "Our present investigation has revealed that high SPINK4 expression is connected to aggressive rectal cancer features and is a unique prognostic biomarker of inferior patient outcomes for those undergoing neoadjuvant CCRT." (PMID 34202399, 2021). "The results revealed that SPINK4 gene expression was considerably upregulated among CCRT nonresponders (p = 0.0001), thus prompting further analysis to elucidate the role of SPINK4 in rectal cancer." (PMID 34202399, 2021). "Accordingly, further analysis is required to dissect the detailed molecular mechanisms underlying the chemoradioresistant and metastatic effects of SPINK4 in rectal cancer." (PMID 34202399, 2021). "Here, we provide the first evidence demonstrating that high SPINK4 expression is significantly related to poor clinical outcomes, and functions as a prognostic biomarker for rectal cancer patients receiving neoadjuvant CCRT." (PMID 34202399, 2021). "Additionally, in rectal cancer patients receiving concomitant chemoradiotherapy, elevated SPINK4 expression predicts a poor treatment response." (PMID 37013514, 2023). "Analogously, low SPINK4 expression might be associated with poor prognosis in CRC patients, but might also be associated with improved outcomes among rectal cancer patients undergoing neoadjuvant CCRT." (PMID 34202399, 2021). "Whether SPINK4 can downregulate HTRA1 to activate the PI3K/AKT pathway involved in rectal cancer metastasis needs further verification." (PMID 34202399, 2021). "Since numerous SPINK members also act as inhibitors of serine protease uPA, whether SPINK4 can dissociate the binding between matrix-bound vitronectin and the uPA receptor to create a metastatic niche in rectal cancer needs to be confirmed." (PMID 34202399, 2021). "However, the correlations among SPINK4 expression, diabetes, and chemoresistance in rectal cancer require further identification." (PMID 34202399, 2021). "We accumulated the cases of 172 rectal cancer patients who received neoadjuvant CCRT followed by surgery and collected tumor specimens for the evaluation of the expression of SPINK4 using immunohistochemistry." (PMID 34202399, 2021). "Therefore, the different, and sometimes paradoxical, expression of SPINK4 appears to be dependent on cell type-specific contexts, providing another explanation for why our results from this rectal cancer cohort seem distinct from those of Wang’s study in a mixed colon and rectal cancer cohort." (PMID 34202399, 2021). "However, the expression of SPINK4 in tumor tissues from patients receiving neoadjuvant CCRT, as well as its practical importance—especially for rectal cancer—are largely unrevealed." (PMID 34202399, 2021). "Nevertheless, more studies are required to verify whether SPINK4 can activate L1CAM through PA inhibition to drive metastasis and CCRT resistance in rectal cancer." (PMID 34202399, 2021). "Therefore, whether SPINK4 can induce chemoresistance and metastasis indirectly through serine protease HTRA1 inhibition in rectal cancer deserves further verification." (PMID 34202399, 2021).
Barrett esophagus (4 papers, 2018 to 2023). Esophageal lesion lined with columnar metaplastic epithelium which is flat or villiform. "Furthermore, in a three-layer epigenome-wide association study, SPINK4 was identified as a risk locus for ulcerative colitis, and a single-cell RNA sequence study revealed that SPINK4 was associated with Barrett's esophagus." (PMID 37013514, 2023). "Moreover, SPINK4 has also been identified as a risk locus for ulcerative colitis and Barrett’s esophagus." (PMID 30976466, 2019). "In the colon and Barrett's esophagus, SPINK4 markers appear before morphologically identifiable goblet cells, which may help identify the early stages of intestinal metaplasia." (PMID 35223512, 2022). "Additionally, SPINK4 and ITLN1 mark cells that precede morphologically identifiable goblet cells in colon and Barrett’s oesophagus, potentially aiding the identification of metaplasia." (PMID 30323168, 2018).
inflammatory bowel disease (3 papers, 2019 to 2024). A spectrum of small and large bowel inflammatory diseases of unknown etiology. "Expression of SPINK4 was also found to be significantly increased in the colon mucosa of an inflammatory bowel disease rat model compared with that in normal rats." (PMID 37013514, 2023). "In addition to being among the 21 most upregulated genes in inflammatory bowel disease (IBD), SPINK4 was the gene that most strongly co-expressed with REG4 in IBD." (PMID 38066386, 2024). "REG4 and SPINK4 have been shown top regulated genes in inflammatory bowel disease (IBD), but with no clear role in development of VTE." (PMID 38066386, 2024).
Alzheimer disease (2 papers, 2019 to 2021). A progressive, neurodegenerative disease characterized by loss of function and death of nerve cells in several areas of the brain leading to loss of cognitive function such as memory and language. "Previous studies have also shown that hyperinsulinemia is related to a higher risk for Alzheimer’s disease, and vice versa, and that high expression of SPINK4 is significantly related to biological processes in Alzheimer’s disease." (PMID 34202399, 2021). "However, the process in Alzheimer’s disease pathway was significantly related to high expression of SPINK4." (PMID 31888570, 2019). "The functional and pathway enrichment analysis of SPINK4 in CRC showed that biological processes such as oxidative phosphorylation, metabolism of some components, and process in Alzheimer’s disease were significantly enriched." (PMID 31888570, 2019).
gastric adenocarcinoma (2 papers, 2019 to 2024). "Western blotting also showed high expression of SPINK4, TTR, PCSK1N, CHGA and GHRL in gastric adenocarcinoma cell lines, with GHRL showing the most significant increase (p < 0.05)." (PMID 38752750, 2024). "The results revealed that SPINK4 expression was higher in pancreatic adenocarcinoma (PAAD) and gastric adenocarcinoma (STAD) tissues than in the corresponding normal tissues." (PMID 31888570, 2019). "In addition to being downregulated in CRC, SPINK4 expression was higher in pancreatic adenocarcinoma (PAAD) and gastric adenocarcinoma than in the corresponding normal tissues at the RNA level." (PMID 31888570, 2019).
gastric cancer (2 papers, 2019 to 2022). A primary or metastatic malignant neoplasm involving the stomach. "Using enzyme-linked immunosorbent assays, we found that the serum SPINK4 level was significantly increased in preoperative CRC compared with postoperative CRC patients, gastric cancer patients, and healthy controls (p < 0.05)." (PMID 30976466, 2019). "In the present study, the serum SPINK4 level was much higher in preoperative CRC patients than in postoperative CRC patients, gastric cancer patients, and healthy controls, suggesting that serum SPINK4 was specifically increased in CRC and decreased after resection of CRC." (PMID 30976466, 2019). "The serum SPINK4 level was highest in preoperative CRC patients compared with postoperative CRC patients, gastric cancer patients, and healthy controls (p < 0.05)." (PMID 30976466, 2019).
pancreatic cancer (2 papers, 2024 to 2025). "Previous studies have suggested an association between serine peptidase inhibitor Kazal type 4 (SPINK4) and various subtypes of pancreatic cancer." (PMID 40608007, 2025).
adenoma (1 paper, 2019). A neoplasm arising from the epithelium. "The results indicated that the relative SPINK4 expression level was decreased in adenoma compared to that in adjacent normal mucosa (4.1 ± 0.1 vs. 4.2 ± 0.1, P = 0.007)." (PMID 31888570, 2019). "Furthermore, SPINK4 mRNA expression was decreased in adenoma compared to that in adjacent normal mucosa in the present study." (PMID 31888570, 2019). "To address the sequential expression changes from normal colonic mucosa to adenoma to carcinoma, we analyzed SPINK4 mRNA expression by comparing 4 pairs of normal colonic mucosa and adenoma tissues and 4 pairs of adenoma and carcinoma tissues from the GSE3880 dataset." (PMID 31888570, 2019). "However, SPINK4 expression was similar between adenoma and carcinoma (4.1 ± 0.0 vs. 4.2 ± 0.1, P = 0.206)." (PMID 31888570, 2019). "Due to the limited sample size of adenoma cases in the present study, whether SPINK4 can be used as a predictor of CRC formation requires further study." (PMID 31888570, 2019). "However, although the expression of SPINK4 in carcinoma tended to be further decreased compared to that in adenoma, the difference was not statistically significant." (PMID 31888570, 2019).
Behcet disease (1 paper, 2024). A chronic, relapsing, multisystemic vasculitis characterized by mucocutaneous lesions, as well as articular, vascular, ocular and central nervous system manifestations. "Further evidence needs to be produced about SPINK4 expression in other colitis pathologies, such as Behcet’s disease." (PMID 38997284, 2024).
bladder cancer (1 paper, 2020). "The remaining 5 genes have not been found to be associated with the prognosis of bladder cancer (BTBD16, OLFML2B, PRRX1, SPINK4, and SPON2)." (PMID 33204728, 2020).